ZNF436 (zinc finger protein 436)
Description:
May be a transcriptional repressor.
Synonyms: KIAA1710; Zfp46; ZNF
Tractability: PROTAC: UniProt records ubiquitination sites on it.
Gene: Protein-coding gene on chromosome 1 (23,359,448 to 23,369,836, reverse strand). Ensembl gene ENSG00000125945.
Subcellular location: Nucleus
Subcellular location (Human Protein Atlas): Cytosol; Nucleoplasm
Pathways (Reactome):
Gene expression (Transcription): Generic Transcription Pathway
Gene Ontology:
Molecular function: protein binding; DNA-binding transcription factor activity, RNA polymerase II-specific; RNA polymerase II transcription regulatory region sequence-specific DNA binding
Biological process: regulation of transcription by RNA polymerase II; regulation of DNA-templated transcription
Cellular component: nucleoplasm; nucleus
Genetic constraint (gnomAD): Loss-of-function variants: 16 observed, 31.37 expected, observed/expected ratio (o/e) 0.51, 90% interval 0.34 to 0.77. The upper end of that interval is the gene's LOEUF score, 0.77, which puts it in group 3 of 6, group 1 being the genes least tolerant of losing a copy. Missense variants: 356 observed, 411.52 expected, observed/expected ratio (o/e) 0.87, 90% interval 0.79 to 0.94. Synonymous variants: 138 observed, 136.11 expected, observed/expected ratio (o/e) 1.01, 90% interval 0.88 to 1.17.
Homologues: Orthologues: chimpanzee ZNF436 (99% identical), macaque ZNF436 (99% identical), dog ZNF436 (98% identical), pig ZNF436 (97% identical), mouse Zfp46 (91% identical). Paralogues in human: ZNF229 (46% identical), ZNF606 (46% identical), ZNF432 (45% identical), ZNF33B (45% identical), ZNF182 (45% identical), ZNF189 (45% identical), ZNF615 (45% identical), RBAK (45% identical), ZNF226 (45% identical), ZNF33A (44% identical), ZNF250 (44% identical), ZNF16 (44% identical), and 164 more.
Diseases named in the same sentence as ZNF436 in open-access papers:
ZNF436 is named in the same sentence as 5 diseases in open-access papers, as found by Europe PMC text mining. Sharing a sentence is not in itself a finding about the gene and the disease. The quoted sentences say what the papers report.
breast carcinoma (1 paper, 2023). "In breast cancer, high ZNF436 expression is associated with high metastasis." (PMID 37904225, 2023).
neuroblastoma (1 paper, 2023). Neuroblastoma (NB) is the most common solid, extracranial childhood tumor. "Consistent with the poor prognosis of 1p36 deletion, lower expression of ZNF436 was associated with worse clinical outcomes of neuroblastoma." (PMID 37904225, 2023). "Results from five independent neuroblastoma cohorts suggested that ZNF436 was detected and was associated with the favorable prognosis of neuroblastoma in E-MTAB-1781, TARGET, GSE16476, GSE62564 and GSE85047 datasets." (PMID 37904225, 2023). "So, in this study, using independent risk factors age of diagnosis, MYCN amplification and ZNF436, we developed a nomogram model to predict the overall survival of neuroblastoma." (PMID 37904225, 2023). "Our results suggested that zinc finger protein 436 (ZNF436) was an independent prognostic marker and was significantly associated with the favorable clinical outcomes of neuroblastoma." (PMID 37904225, 2023). "Higher ZNF436 expression was associated with the longer event free survival and overall survival of neuroblastoma." (PMID 37904225, 2023). "Moreover, zinc finger protein 436 (ZNF436) located at 1p36 region was down-regulated in 1p deleted neuroblastoma and higher ZNF436 expression was associated with the longer event free survival and overall survival of neuroblastoma." (PMID 37904225, 2023). "A nomogram risk model based on age, MYCN amplification and ZNF436 could predict the overall survival of neuroblastoma with higher specificity and sensitivity." (PMID 37904225, 2023). "Our results provided new prognostic functions of ZNF436 in neuroblastoma and those prognostic functions may be associated with unique MYCN amplification and 1p deletion." (PMID 37904225, 2023). "Finally, we showed that a nomogram risk model based on age, MYCN amplification and ZNF436 could predict the overall survival of neuroblastoma with high specificity and sensitivity." (PMID 37904225, 2023). "All those results highlighted the sub-types and overall survival predictions of ZNF436 in neuroblastoma." (PMID 37904225, 2023). "We then constructed a nomogram model based on age of diagnosis, MYCN amplification and ZNF436 to predict the overall survival of neuroblastoma in E-MTAB-1781, TARGET, GSE16476 and GSE62564 datasets." (PMID 37904225, 2023). "The predictions of MYCN amplification and overall survival of neuroblastoma based on ZNF436 expression were validated in TARGET, GSE16476 and GSE62564 datasets." (PMID 37904225, 2023). "ZNF436 was down-regulated in MYCN amplified neuroblastoma patients in E-MTAB-1781, GSE13136, GSE73517, TARGET, GSE16476, GSE62564 and GSE85047 datasets." (PMID 37904225, 2023). "ZNF436 was down-regulated in 1p deleted neuroblastoma and ZNF436 was lower in neuroblastoma patients with MYCN amplification or age at diagnosis ≥ 18months, or with stage 4 neuroblastoma." (PMID 37904225, 2023). "The prognostic effects of ZNF436 in neuroblastoma were further validated using TARGET, GSE16476, GSE62564 and GSE85047 datasets." (PMID 37904225, 2023). "So, we determined the ZNF436 expressions in different sub-types of neuroblastoma using seven independent neuroblastoma cohorts." (PMID 37904225, 2023). "The associations of age of diagnosis, MYCN amplification, 1p deletion and ZNF436 expression in the prediction of the overall survival of neuroblastoma were further analyzed using multivariate cox regression assay." (PMID 37904225, 2023). "The expression levels of ZNF436 were lower in neuroblastoma patients with MYCN amplification or age at diagnosis ≥ 18months, or with stage 4 neuroblastoma." (PMID 37904225, 2023). "Only ZNF436 was involved in the prognosis of neuroblastoma in all E-MTAB-1781, TARGET, GSE16476, GSE62564 and GSE85047 datasets." (PMID 37904225, 2023). "The Kaplan-Meier survival analysis was further used to validate the favorable prognosis of ZNF436 in neuroblastoma." (PMID 37904225, 2023).
neuroblastoma (continued). "Combinations of ZNF436 expression with MYCN amplification or age of diagnosis achieved better prognosis of neuroblastoma." (PMID 37904225, 2023). "On the contrary, neuroblastoma patients with ZNF436 low expressions and with MYCN amplification had significantly shorter overall survival in E-MTAB-1781 and TARGET datasets." (PMID 37904225, 2023). "Based on MYCN amplification and ZNF436 expression level, neuroblastoma patients were classified into different sub-groups." (PMID 37904225, 2023). "Neuroblastoma patients with ZNF436 higher expression levels had prolonged event free survival contrast with ZNF436 lowly expressed neuroblastoma patients in E-MTAB-1781 dataset." (PMID 37904225, 2023). "Neuroblastoma patients with age at diagnosis ≥ 18months and with ZNF436 lower expressions had the worst prognosis in E-MTAB-1781, TARGET and GSE62564 datasets." (PMID 37904225, 2023). "Also, contrast with stage 1 and stage 2 neuroblastoma, ZNF436 was down-regulated in stage 4 neuroblastoma patients in E-MTAB-1781, GSE13136, GSE73517, TARGET, GSE16476, GSE62564 and GSE85047 datasets." (PMID 37904225, 2023). "Also, neuroblastoma patients with ZNF436 higher expression levels had prolonged overall survival contrast with ZNF436 lowly expressed neuroblastoma patients in E-MTAB-1781 dataset." (PMID 37904225, 2023). "However, compared with stage 4, ZNF436 expressions in stage 4s neuroblastoma in E-MTAB-1781, GSE13136, GSE73517, TARGET, GSE16476, GSE62564 and GSE85047 datasets were not significantly different." (PMID 37904225, 2023). "Therefore, the detailed roles of ZNF436 should be further revealed using neuroblastoma cells and neuroblastoma patients." (PMID 37904225, 2023). "Our previous results suggested that ZNF436 was associated with the overall survival of neuroblastoma and showed the synergistic prognostic effects of ZNF436 with MYCN amplification or age of diagnosis in neuroblastoma." (PMID 37904225, 2023). "Since, age of diagnosis, MYCN amplification and ZNF436 expression were independent prognostic factors in most neuroblastoma cohorts, we speculated the superior prognostic effects in the combinations of ZNF436 with MYCN amplification or age of diagnosis." (PMID 37904225, 2023). "Similar with E-MTAB-1781 dataset, neuroblastoma patients with ZNF436 higher expression levels had prolonged event free survival and overall survival, contrast with ZNF436 lowly expressed neuroblastoma patients in TARGET, GSE16476, GSE62564 and GSE85047 datasets." (PMID 37904225, 2023). "Chromosome 1p36 candidate gene ZNF436 was a prognostic maker of neuroblastoma." (PMID 37904225, 2023). "The ROC analysis in E-MTAB-1781 dataset indicated that ZNF436 could distinguish 1p deleted from 1p normal neuroblastoma patients with high specificity and sensitivity." (PMID 37904225, 2023). "Moreover, contrast with stage 1 and stage 2 neuroblastoma, ZNF436 was down-regulated in stage 3 neuroblastoma patients in E-MTAB-1781, TARGET, GSE16476, GSE62564 and GSE85047 datasets." (PMID 37904225, 2023). "Also, in E-MTAB-1781, GSE13136, GSE73517, TARGET, GSE16476, GSE62564 and GSE85047 datasets, the expression levels of ZNF436 were lower in neuroblastoma patients with age at diagnosis ≥ 18months than neuroblastoma patients with age at diagnosis < 18months." (PMID 37904225, 2023). "Our results suggested that ZNF436 was served as prognostic biomarker of neuroblastoma." (PMID 37904225, 2023). "Furthermore, ZNF436 also could predict the the three years, five years or ten years overall survival of neuroblastoma with high accuracy in E-MTAB-1781 dataset." (PMID 37904225, 2023). "Furthermore, ZNF436 also could predict the three years, five years or ten years overall survival of neuroblastoma with high accuracy in GSE16476 and GSE62564 datasets." (PMID 37904225, 2023). "Our results suggested that ZNF436 was down-regulated with genetic 1p deletion or MYCN amplification and served as a favorable prognostic marker of neuroblastoma." (PMID 37904225, 2023).
neuroblastoma (continued). "Further, we attempted to determine the accuracy of ZNF436 in the prediction of 1p deletion, MYCN amplification and in the prediction of the overall survival of neuroblastoma." (PMID 37904225, 2023). "Combinations of ZNF436, MYCN amplification or age at diagnosis achieved better prognosis in neuroblastoma." (PMID 37904225, 2023). "ZNF436 was an independent prognostic factor of neuroblastoma in TARGET, GSE16476 and GSE62564 neuroblastoma cohorts." (PMID 37904225, 2023). "In TARGET, GSE16476 and GSE62564 neuroblastoma cohorts, ROC curves showed the high specificity and sensitivity of ZNF436 in distinguishing MYCN amplified from MYCN non-amplified neuroblastoma patients." (PMID 37904225, 2023). "Neuroblastoma patients with ZNF436 high expressions and without MYCN amplification had significantly longer overall survival in E-MTAB-1781 and TARGET datasets." (PMID 37904225, 2023). "Age of diagnosis, MYCN amplification and 1p deletion were independent prognostic factors of neuroblastoma, while, ZNF436 was not an independent prognostic factor of neuroblastoma in E-MTAB-1781 dataset." (PMID 37904225, 2023). "Similar predictive specificity and sensitivity of ZNF436 in distinguishing MYCN amplified from MYCN non-amplified neuroblastoma patients was determined in E-MTAB-1781 dataset." (PMID 37904225, 2023). "ZNF436 had robust predictive values of MYCN amplification and overall survival of neuroblastoma." (PMID 37904225, 2023). "Moreover, the expression levels of ZNF436 were lower in neuroblastoma with MYCN amplification or age at diagnosis ≥ 18months, or in stage 4 neuroblastoma." (PMID 37904225, 2023). "However, ZNF436 was a prognostic factor of neuroblastoma in E-MTAB-1781 dataset independent of age of diagnosis and MYCN amplification." (PMID 37904225, 2023). "Furthermore, the prognostic significance of ZNF436 in neuroblastoma was independent of MYCN amplification and age of diagnosis." (PMID 37904225, 2023). "The functions of ZNF436 in neuroblastoma are never reported." (PMID 37904225, 2023).
cancer (1 paper, 2022). A tumor composed of atypical neoplastic, often pleomorphic cells that invade other tissues. "Transcription factor targets included NR1H4, ZMYM2 and ZNF436, which might be metabolism-related and cancer-related factors." (PMID 35410157, 2022).
ZNF436 also shares sentences with these, for which no sentence is quoted: glioma (1 paper); tumor (1).